RELN (reelin)
Diseases named in the same sentence as RELN in open-access papers (continued):
Sharing a sentence is not in itself a finding about the gene and the disease.
liver cancer (1 paper, 2020). An epithelial or non-epithelial malignant neoplasm that arises from the liver. "The downregulation of Reelin has been found to be related to cell migration ability, tumour invasiveness and patients’ survival rates in several cancers, including gastric, breast, pancreatic and liver cancers." (PMID 32321427, 2020).
lymphangioma (1 paper, 2007). A benign lesion composed of dilated lymphatic channels. "LECs from foreskin and lymphangioma had an almost identical pattern of lymphendothelial markers such as podoplanin, Prox1, reelin, cMaf and integrin-α1 and -α9." (PMID 17584927, 2007).
Macrocephaly (1 paper, 2022). Occipitofrontal (head) circumference greater than 97th centile compared to appropriate, age matched, sex-matched normal standards. "In this study, we describe the functional analysis of a de novo splice site variant identified in the CACNA1H gene in an individual with ASD and macrocephaly who also carries deleterious compound heterozygous missense variants in the RELN gene." (PMID 35668055, 2022). "Recently, we have identified in one Brazilian individual with autism and macrocephaly rare compound heterozygous missense variants in the RELN gene and a de novo splice site variant in the CACNA1H gene." (PMID 35668055, 2022).
meningioma (1 paper, 2012). A generally slow growing tumor attached to the dura mater. "All of investigated ECM genes except RELN were found with significantly higher expression in anaplastic meningiomas than in arachnoidal tissue." (PMID 23285163, 2012).
meningitis (1 paper, 2026). A disorder characterized by acute inflammation of the meninges of the brain and/or spinal cord. "Overall, the findings suggest that MI altered MMP-2/3/9 activity, H3K4me3, and the methylation of Reln, thereby affecting reelin, synaptic protein expression, and motor coordination in an experimental meningitis rat model." (PMID 42123345, 2026).
metabolic syndrome (1 paper, 2025). A cluster of metabolic risk factors for CARDIOVASCULAR DISEASES and TYPE 2 DIABETES MELLITUS. "Therefore, it is necessary to study the link between RELN gene expression and the metabolic syndrome." (PMID 39897195, 2025).
myopia (1 paper, 2024). "Reelin functions downstream of TGF-β1, and the opposite expression found in this study might indicate an increased level of TGF-β, which is associated with myopia in remodeling the sclera during myopia development." (PMID 39408973, 2024).
neurodegenerative eye diseases (1 paper, 2025). "Comparisons and correlation studies were used to verify the hypothesis of a Reelin, Aβ1-42, TAU and FTH1 marker expressions in this vitreoretinal disease, extending the knowledge on the pathological spectrum of neurodegenerative eye diseases." (PMID 40867631, 2025).
Neurofibrillary tangles (1 paper, 2025). Pathological protein aggregates formed by hyperphosphorylation of a microtubule-associated protein known as tau, causing it to aggregate in an insoluble form. "One of the enhanced proteins, ITSN1, is a key component of the Reelin signaling pathway and thus may have the potential to act in conjunction with sCLU to reduce levels of p-tau and thus neurofibrillary tangle formation." (PMID 40322539, 2025).
nevus (1 paper, 2017). Nevus (or naevus, plural nevi or naevi, from nævus, Latin for "birthmark") is the medical term for sharply circumscribed[1] and chronic lesions of the skin or mucosa. "The data collected in this study did not allow any assumptions regarding either the significance or the pathogenic role of reelin present in the nevus cells, or the origin of reelin in these cells." (PMID 28255385, 2017). "The demonstration of the presence of reelin in nevus cells, as well as the investigation of its role in neuronal migration in adult life, opened new study prospects in tumoral proliferation and invasivity." (PMID 28255385, 2017). "Little is still known regarding the presence and involvement of reelin in the maintenance of nevus architecture and in the proliferation, migration, and metastatic development of melanocytes from skin melanocytic nevi." (PMID 28255385, 2017). "Our study showed that reelin was massively expressed in nevus cells (number of cases, intensity of expression)." (PMID 28255385, 2017). "The presence of reelin in the nevus cells was correlated only with nevus dysplasia, assessed by clinical and histological criteria." (PMID 28255385, 2017). "Our study showed the presence of reelin in nevus cells from cutaneous melanocytic nevi and, in these cells, only the VLDLR receptor was present in half of the cases." (PMID 28255385, 2017). "The significance of the reelin presence in cutaneous nevus cells may be hypothetically considered correlated with the position maintenance of the nevus cells or migration of these cells in malignant transforming situation." (PMID 28255385, 2017). "In our study, we investigated the reelin presence in melanocytes from cutaneous nevi considering that reelin may have an important role in malign or non-malign evolution of these naevi." (PMID 28255385, 2017). "We investigated the reelin presence and its receptors, VLDLR and ApoER2, in melanocytic nevi considering the neural crest origin of the nevus cells and their migration into skin during embrionary period." (PMID 28255385, 2017). "Reelin was found in 91% of the nevus cells (29/ 32) and was absent in 9% of the cases (3/ 32)." (PMID 28255385, 2017).
oligodendroglioma (1 paper, 2012). A well-differentiated (WHO grade II), diffusely infiltrating neuroglial tumor, typically located in the cerebral hemispheres. "Three additional gene transcripts, CAP2, RELN and SIDT1, showed >20-fold increase in the level of latent splicing in Grade III oligodendroglioma compared to normal cells." (PMID 23002147, 2012).
polyp (1 paper, 2022). A usually exophytic mass attached to the underlying tissue by a broad base or a thin stalk. "As in human colons, the shift from reelin upregulation to repression occurs in the progression from polyp to the tumoral lesion." (PMID 36290310, 2022).
post-partum depression (1 paper, 2024). "This led us to hypothesize a potential link between reelin and the oxytocinergic system, which could play a crucial role in the pathophysiology of post-partum depression." (PMID 39228796, 2024). "Additionally, we present data indicating that peripheral reelin administration restores behavioral and neurochemical alterations induced by chronic corticosterone exposure, showing novel antidepressant-like effects of reelin in a preclinical model for post-partum depression." (PMID 39228796, 2024). "Thus, the ability of reelin alone to produce such antidepressant effects is promising, suggesting a putative use of reelin as a rapid-acting antidepressant comparable to ketamine to treat post-partum depression, with potentially better efficacy and safety profile than fluoxetine." (PMID 39228796, 2024).
preeclampsia (1 paper, 2026). Preeclampsia is a hypertensive disorder of pregnancy that is characterized by new-onset hypertension with proteinuria presenting after 20 weeks of gestation, and depending on mild or severe forms may initially present with severe headache, visual disturbances, and hyperreflexia. "In the plasma of first-trimester pregnant women, Reelin levels were lower in patients with severe preeclampsia (PE) at a time before the onset of PE clinical symptoms." (PMID 41888978, 2026).
prion disease (1 paper, 2025). A transmissible disease that is caused by a protein that is able to induce abnormal folding of normal cellular proteins, leading to characteristic spongiform brain changes, which are associated with neuronal loss without an inflammatory response. "The Reelin signaling pathway, implicated both in Alzheimer’s and prion diseases, engages Dab1, an adaptor protein influencing APP processing and amyloid beta deposition." (PMID 40733546, 2025). "We showed that prion disease strongly impairs the Reelin signaling cascade, with a prominent reduction in Dab1 protein expression." (PMID 40733546, 2025). "This suggests a discrepancy between Reelin expression levels and Dab1 phosphorylation status, indicating potential dysfunction in the Reelin signaling pathway in the context of prion diseases." (PMID 40733546, 2025). "Taken together, our findings suggest that Reelin processing may also play a role in prion diseases, thus supporting the hypothesis that the Reelin signaling pathway is involved in the pathogenesis of several neurodegenerative diseases." (PMID 40733546, 2025). "Interestingly, reduced Dab1 expression is already pronounced in the pre-symptomatic stage of the infection, possibly suggesting that Reelin pathway disruption is an early event of prion diseases." (PMID 40733546, 2025). "Interestingly, it has been reported that the Reelin signaling pathway is involved in both Alzheimer’s and prion diseases." (PMID 40733546, 2025). "This raises the hypothesis that increased meprin-β or other proteolytic activity may contribute to the observed Reelin fragmentation in prion disease." (PMID 40733546, 2025). "Moreover, the role of the Reelin signaling cascade in mouse models of prion disease was investigated." (PMID 40733546, 2025). "Although the role of the Reelin signaling cascade in prion diseases has not been deeply investigated, it has been reported that APP processing and β-amyloid deposition in sporadic Creutzfeldt-Jakob disease (CJD) patients are dependent on Dab1." (PMID 40733546, 2025). "Finally, as the role of the Reelin/Dab1 signaling cascade in prion diseases has not been deeply investigated, RML-inoculated mice were used as prion pathology models." (PMID 40733546, 2025). "Further research is necessary to fully elucidate the intricate relationship between Reelin expression, Dab1 phosphorylation, and disease pathology in neurodegenerative conditions like prion diseases, as the expression levels of Reelin alone are not considered to be diagnostic markers." (PMID 40733546, 2025).
psoriasis (1 paper, 2020). An autoimmune condition characterized by red, well-delineated plaques with silvery scales that are usually on the extensor surfaces and scalp. "This analysis produced a list of 9 significantly altered canonical pathways (p < 0.05 or –log p-value > 1.30) including SAPK/JNK signaling, NAD biosynthesis and salvage pathway, phototransduction pathway, VDR/RXR activation, Reelin signaling in neurons, and role of IL-17A in psoriasis." (PMID 32260415, 2020).
pterygium (1 paper, 2020). A wedge-shaped fibrovascular lesion arising from the bulbar conjunctiva and extending to the cornea. "There are 6 genes that are highly expressed in pterygium, MYC, CDH2, CCNB1, RELN, RB1, and ERBB4." (PMID 33299863, 2020). "We presume that the LINC00472 network might function in pterygium via the FOXM1 PATHWAY, especially through the regulation of CCNB1, MYC, ERBB4, RELN, RB1, and CDH2 in the ceRNA network." (PMID 33299863, 2020).
renal hypoplasia (1 paper, 2025). Renal hypoplasia is a developmental anomaly in which one or both kidneys (unilateral or bilateral renal hypoplasia, respectively) have a deficit in the number of nephrons and may be small. "Our objective was to determine if these proteins engage with Reelin–Dab1 signaling to facilitate renal hypoplasia and influence the development of CAKUT." (PMID 40650197, 2025).
retinal disease (1 paper, 2014). "In line with recent and the herein presented data, we propose E-reeler mice as a good “retinal disease” model to explore the cross-talk between NGF and Reelin." (PMID 24627687, 2014).
retinal ischemia (1 paper, 2025). A ischemic disease that involves the retina. "In this study, we demonstrate for the first time the neuroprotective role of Reelin protein in promoting the survival of retinal neurons, a significant advancement in addressing retinal ischemia." (PMID 40442071, 2025).
small cell lung carcinoma (1 paper, 2025). Small cell lung cancer (SCLC) is a highly aggressive malignant neoplasm, accounting for 10-15% of lung cancer cases, characterized byrapid growth, and early metastasis. "Brain metastases of small cell lung cancer (SCLC) have been shown to secrete REELIN (RELN), which recruits reactive astrocytes and activates developmental programs in these cells." (PMID 40917877, 2025).
teratoma (1 paper, 2022). A non-seminomatous germ cell tumor characterized by the presence of various tissues which correspond to the different germinal layers (endoderm, mesoderm, and ectoderm). "In our study, CARD11(caspase recruitment domain family member 11) (mutated in 18% intracranial teratomas), IRS1(insulin receptor substrate 1) (18%), PSMD11(16%), RELN(16%), RRAS2(16%), SMC1A(16%), SYNE1(16%) and ZFHX3(16%) were the tumor-related genes with the highest mutation rates in our cohort." (PMID 36457486, 2022).
thrombosis (1 paper, 2023). "In non-COVID studies, we and others demonstrated that circulating Reelin promotes leukocyte infiltration and thrombosis." (PMID 37441066, 2023).
triple-negative breast carcinoma (1 paper, 2021). An invasive breast carcinoma which is negative for expression of estrogen receptor (ER), progesterone receptor (PR), and human epidermal growth factor receptor 2 (HER2). "RELN mRNA was significantly increased upon RNAi-mediated α3 knockdown in two triple-negative breast cancer cell lines, MDA-MB-231 and SUM159." (PMID 33477804, 2021).
type 2 diabetes (1 paper, 2023). "Because of the proximity of RELN to rs2891691, we evaluated the sex-specific association with type 2 diabetes and tested for heterogeneity between sex-specific allelic effects using GWAMA v2.2.2." (PMID 37148359, 2023).
cancer (54 papers, 2006 to 2025). A tumor composed of atypical neoplastic, often pleomorphic cells that invade other tissues. "FAT3 and RELN, well-known tumor suppressors and mutated genes, are closely linked to poor prognosis in various cancer types, including TBNC." (PMID 39061186, 2024). "The result showed KAT6B|RELN pair was an independent risk factor in five cancers (CESC, SARC, LIHC, LUAD, and PRAD)." (PMID 36139377, 2022). "This is in line with a study that postulated an association between the RELN pathway and the tumorigenesis of several different cancers, including PDAC." (PMID 34357098, 2021). "The expression of Reelin in cancer-associated fibroblasts (ReelinCAF) and tumor cells (ReelinTC) was analyzed by the Gene Expression Omnibus (GEO) database." (PMID 34485127, 2021). "We discovered that RELN mutations may be a potential biomarker for cancer immunotherapeutic efficacy prediction." (PMID 36497098, 2022). "Interestingly, TGF-β signaling has been inversely linked to RELN expression in cancer cells." (PMID 33477804, 2021). "By using markers of specific clusters, we identified five distinct cell types, including cancer‐associated fibroblasts (CAFs) (COL1A1), endothelial cells (PECAM1), epithelial cells (CDH1), immune cells (PTPRC), and neurons (RELN)." (PMID 40038875, 2025). "Pathways related to neuronal biology, such as Myelination Signaling, Reelin Signaling in Neurons, Endocannabinoid Developing Neuron Pathway and Opioid Signaling Pathway, were also significantly enriched in the cancer compartment of PNI foci." (PMID 40075699, 2025). "Even though reelin’s expression is restricted to brain cells, recent studies showed that BrM cancer cells can acquire a neuronal-like metaprogram and express brain-specific proteins to adapt to the microenvironment of the brain." (PMID 37728789, 2023). "Reelin is an extracellular glycoprotein that is involved in regulating neuronal migration during brain development and also in cancer biology." (PMID 36474619, 2022). "Most studies on changes in reelin expression in cancers have only looked at a particular stage of the cancer process, those measuring reelin expression during cancer progression being very few." (PMID 36290310, 2022). "In the second dataset, LUSC, PIK3CA (46.5%), EGFR (7%), PDE4DIP (6.6%), KRAS (4.4%), and RELN (4.4%) were labeled with copy number gain, while CDKN2A (27.9%), LRP1B (17.4%), PTEN (9.8%), and PTPRD (9%) appeared to be the cancer genes with copy number loss." (PMID 35330454, 2022). "Among cancer-related genes, CARD11(18%) and IRS1(18%) were the most common somatic mutated genes, followed by PSMD11, RELN, RRAS2, SMC1A, SYNE1 and ZFHX3, and the mutation rates of the latter six genes were all 14%." (PMID 36457486, 2022). "Considering that the role of Reelin in TCs was contrary to that in CAFs in cancer metastasis and relapse, we further evaluated its prognostic value in OS and DSS." (PMID 34485127, 2021). "Together, our findings identify a novel role for integrin α3β1 in the modulation of the cancer cell secretome through repression of the RELN gene, leading to reduced secretion of Reelin and promoting invasion of TNBC cells." (PMID 33477804, 2021). "We found correlations of RELN with 28 types of TILs across human heterogeneous cancers according to the TISIDB database." (PMID 34485127, 2021). "RELN is an extracellular glycoprotein that plays a vital role in neuronal migration and has been shown to be downregulated in many cancers." (PMID 32324757, 2020). "Twelve genes were located in eight of the top-15 breakpoint regions, and six of these genes are associated with cancer (CACNA1B, IBSP, MEPE, NBEA, RELN and THSD7A)." (PMID 31249626, 2019). "The activation of FAK/Syk/Akt/mTOR and STAT3 pathways contributes to Reelin-induced cancer cell growth and metabolic reprogramming." (PMID 28345605, 2017).